GLUL (glutamate-ammonia ligase)
Description:
Glutamine synthetase that catalyzes the ATP-dependent conversion of glutamate and ammonia to glutamine. Its role depends on tissue localization: in the brain, it regulates the levels of toxic ammonia and converts neurotoxic glutamate to harmless glutamine, whereas in the liver, it is one of the enzymes responsible for the removal of ammonia (By similarity). Plays a key role in ammonium detoxification during erythropoiesis: the glutamine synthetase activity is required to remove ammonium generated by porphobilinogen deaminase (HMBS) during heme biosynthesis to prevent ammonium accumulation and oxidative stress (By similarity). Essential for proliferation of fetal skin fibroblasts. Independently of its glutamine synthetase activity, required for endothelial cell migration during vascular development: acts by regulating membrane localization and activation of the GTPase RHOJ, possibly by promoting RHOJ palmitoylation. May act as a palmitoyltransferase for RHOJ: able to autopalmitoylate and then transfer the palmitoyl group to RHOJ. Plays a role in ribosomal 40S subunit biogenesis. Through the interaction with BEST2, inhibits BEST2 channel activity by affecting the gating at the aperture in the absence of intracellular L-glutamate, but sensitizes BEST2 to intracellular L-glutamate, which promotes the opening of BEST2 and thus relieves its inhibitory effect on BEST2.
Synonyms: GS; GLNS; DEE116; PIG43; PIG59
Tractability: Small molecule: a structure with a bound ligand is known; it has a high-quality binding pocket; it belongs to a druggable protein family. Antibody: UniProt places it where antibodies can reach, with high confidence; its Gene Ontology location is reachable by antibodies, with high confidence; the Human Protein Atlas places it where antibodies can reach. PROTAC: UniProt records ubiquitination sites on it; ubiquitination databases record sites on it; its protein half-life has been measured; a small molecule that binds it is known.
Target class: Enzyme; Ligase
Gene: Protein-coding gene on chromosome 1 (182,378,098 to 182,392,206, reverse strand). Ensembl gene ENSG00000135821.
Subcellular location: Cytoplasm, cytosol; Microsome; Mitochondrion; Cell membrane
Subcellular location (Human Protein Atlas): Cytosol; Mitochondria; Connecting piece; Plasma membrane
Pathways (Reactome):
Metabolism: Glutamate and glutamine metabolism
Neuronal System: Astrocytic Glutamate-Glutamine Uptake And Metabolism
Gene Ontology:
Molecular function: glutamine synthetase activity; identical protein binding; protein binding; protein-cysteine S-palmitoyltransferase activity; catalytic activity
Biological process: cell population proliferation; protein palmitoylation; regulation of endothelial cell migration; regulation of protein localization to nucleolus; regulation of sprouting angiogenesis; ribosome biogenesis; intracellular ammonium homeostasis; L-glutamate catabolic process; L-glutamine biosynthetic process; positive regulation of erythrocyte differentiation
Cellular component: cytosol; extracellular exosome; nucleus; plasma membrane; mitochondrion
Genetic constraint (gnomAD): Loss-of-function variants: 7 observed, 34.89 expected, observed/expected ratio (o/e) 0.2, 90% interval 0.11 to 0.38. The upper end of that interval is the gene's LOEUF score, 0.38, which puts it in group 1 of 6, group 1 being the genes least tolerant of losing a copy. Missense variants: 292 observed, 487.26 expected, observed/expected ratio (o/e) 0.6, 90% interval 0.54 to 0.66. Synonymous variants: 168 observed, 167.49 expected, observed/expected ratio (o/e) 1, 90% interval 0.88 to 1.14.
Gene-disease validity (ClinGen):
ClinGen rates the evidence that GLUL causes each of these diseases.
congenital brain dysgenesis due to glutamine synthetase deficiency (autosomal recessive): Moderate.
genetic developmental and epileptic encephalopathy (autosomal dominant): Moderate. A complex neurodevelopmental disorder characterized by a range of developmental delays and epileptic encephalopathy phenotypes.
Homologues: Orthologues: chimpanzee GLUL (100% identical), macaque GLUL (100% identical), dog GLUL (97% identical), pig GLUL (97% identical), guinea pig GLUL (96% identical), rabbit GLUL (95% identical), mouse Glul (95% identical), rat Glul (92% identical), zebrafish glulb (87% identical), tropical clawed frog glull (86% identical), zebrafish glula (85% identical), Drosophila melanogaster Gs2 (64% identical), and 4 more. Paralogues in human: LGSN (20% identical).
Diseases named in the same sentence as GLUL in open-access papers:
GLUL is named in the same sentence as 184 diseases in open-access papers, as found by Europe PMC text mining. Sharing a sentence is not in itself a finding about the gene and the disease. The quoted sentences say what the papers report.
epilepsy (29 papers, 2007 to 2025). A brain disorder characterized by episodes of abnormally increased neuronal discharge resulting in transient episodes of sensory or motor neurological dysfunction, or psychic dysfunction. "Although GLUL is a key enzyme in glutamine synthesis, roles for GLUL independent of metabolic enzymes in gastric cancer, lung cancer, epilepsy, and angiogenesis have been revealed by multiple studies." (PMID 40646162, 2025). "In addition, further investigations are needed to unveil the precise mechanism behind ERβ-mediated regulation of GLUL in female epilepsy." (PMID 33897900, 2021).
breast carcinoma (26 papers, 2011 to 2025). "GLUL is downregulated by the drugs, whereas its enhanced expression in breast cancer is associated with a larger tumor size and higher expression of HER2." (PMID 37626832, 2023). "GLUL encodes for glutamine synthetase (GS) and is overexpressed in ER positive luminal breast cancer subtypes and cell lines compared to the basal subtype and cell lines." (PMID 25122196, 2014). "Another gene, GLUL encodes the enzyme glutamine synthetase which is highly expressed both in normal breast luminal epithelial cells and in luminal breast cancer." (PMID 23460839, 2013). "Expression patterns of GLUL protein in human breast cancer tissues were further confirmed by immunohistochemistry (IHC) staining provided by the Human Protein Atlas database." (PMID 36619229, 2023). "Experimental data also confirmed that the knockdown of GLUL in breast cancer cell lines decreased cell proliferation and influenced expressions of specific downstream molecules." (PMID 36619229, 2023). "Results of bioinformatics analyses also revealed the molecular subtype specific for each cell line, as well as DNA methylation levels of GLUL in breast cancer." (PMID 36619229, 2023). "Expression of GLUL was higher in breast cancer samples compared to normal breast, especially in the ER+ breast cancer patients." (PMID 36619229, 2023). "Collectively, our study demonstrated the crucial roles of GLUL, which provide new targets for the treatment of tamoxifen-resistant breast cancer patients." (PMID 36619229, 2023). "Recent studies have shown that expression of GLUL is maintained in some malignancies, such as luminal breast cancer." (PMID 37780942, 2023). "When extracellular glutamine levels decline in preclinical models of breast cancer, asparagine becomes essential for supporting de novo glutamine biosynthesis via upregulation of glutamine synthetase (GLUL)." (PMID 36358940, 2022). "In breast cancer cells, glutamine synthetase (GLUL) was identified as strongly down-regulated by hypoxia and correlated to HIF stabilization." (PMID 31083487, 2019). "Increased GLUL expression has been reported as an early marker of hepatocellular carcinoma, promoting breast cancer cell proliferation, and also found to be an unfavorable prognostic marker in patients with glioblastoma multiforme (GBM) and ovarian cancer." (PMID 31817360, 2019). "In summary, when glutamine and glucose are abundant, MYC promotes their uptake and uniquely controls GLS and GLUL expression in antiestrogen resistant breast cancer cells." (PMID 25339305, 2014). "However, how GLUL regulates the tumor microenvironment for tamoxifen-resistant ER+ breast cancer remains unexplored." (PMID 36619229, 2023). "Regarding our findings, limited glucose resources and GLUL suppression decrease GSTM3 expression as a known metastatic gene in luminal breast cancer, and these findings further accentuate the significant role of GSTM3 in invasion potency, a major step in metastasis." (PMID 37780942, 2023). "MYC regulation of GLS and GLUL in antiestrogen resistant breast cancer cells was unexpected." (PMID 25339305, 2014). "Besides, the M2‐like phenotype TAM could be rewired to antitumor and further reduced cancer cell metastasis on mice‐bearing metastatic lung, skin, and breast cancer by GLUL inhibitor." (PMID 36587392, 2023). "In luminal breast cancer cells, the transcription factor GATA3 activates the expression of glutamine synthase (GLUL) to facilitate glutamine production, thereby reducing the dependence on extracellular glutamine." (PMID 39272886, 2024). "Here, we showed that knockdown of GLUL induced drug resistance in A549 (NSCLC) and HCC1954 (breast cancer) cells." (PMID 31817360, 2019). "To correlate glutamine levels with breast cancer subtype, we first analyzed the expression of GLS and GLUL as reported in The Cancer Genome Atlas (TCGA) database." (PMID 28950000, 2017).
breast carcinoma (continued). "Our analysis revealed that, unlike HER2 positive, Luminal A, Luminal B, or normal-like cancer types, many of the basal subtype breast cancer samples consistently displayed simultaneous up- and down- regulation of GLS and GLUL gene expression, respectively." (PMID 28950000, 2017). "The expression of GLUL and GLS are inversely correlated in the luminal and basal types of primary breast cancers, cancer cell lines, and primary epithelial cells." (PMID 21852960, 2011). "Here we suppressed GLUL expression by siRNA and evaluated the simultaneous effects of GLUL knockdown and restricted glucose levels in MCF7 cells as a model for the luminal A breast cancer subtype." (PMID 37780942, 2023). "While in prostate cancer cells, MYC knockdown was shown to decrease GLS and increase GLUL protein levels, in our antiestrogen resistant breast cancer cell models (LCC9, LCC2, and LY2) we observed the reverse effect – MYC knockdown increased GLS and decreased GLUL protein levels." (PMID 25339305, 2014). "We next examined whether the expression patterns of GLUL, GLS and GLS2 found in luminal and basal cell lines were also reflected in the respective subtypes of primary human breast cancers." (PMID 21852960, 2011). "However, evidence about the roles of GLUL in tamoxifen resistance or recurrence of breast cancer is still absent." (PMID 36619229, 2023).
Hyperammonemia (26 papers, 2015 to 2025). An increased concentration of ammonia in the blood. "Genetic deletion of liver GLUL in mice is sufficient to produce hyperammonemia." (PMID 37343102, 2023).
depression (20 papers, 2009 to 2025). "Contrary to our finding in the cortices of suicide victims, decreased glutamine synthetase (GLUL) levels have been detected in schizophrenia and depression models, and down-regulated GLUL gene has been found among depressed suicide victims." (PMID 23272063, 2012). "In summary, we observed a global up-regulation of AMPA receptors and a global down-regulation of the GRM3 receptor and the glutamine synthase (GLUL) genes expression in the suicide with major depression group." (PMID 19668376, 2009). "Moreover, in patients with depression, a decrease in brain GLUL mRNA expression has been observed in specific regions." (PMID 30307711, 2018). "Microarray studies has shown that altered expression of GLUL in major depressive disorder." (PMID 23521751, 2013). "We also observed for the suicide with major depression group a general up-regulation of AMPA receptors subunit genes and a global down-regulation of GRM3 receptors and glutamine synthase (GLUL) gene expression." (PMID 19668376, 2009).
diabetes (18 papers, 2012 to 2025). "The finding of diabetes-specific CAD-loci, such as GLUL, has also led to the identification of promising new targets that might hopefully result in the development of specific therapies to reduce CVD burden in patients with diabetes." (PMID 36143187, 2022).
hepatocellular carcinoma (18 papers, 2008 to 2025). A malignant tumor that arises from hepatocytes. "Previous studies have shown that in hepatocellular carcinoma, the mechanism by which GLUL increases the HBP flux is that GLUL increases glutamine synthesis via its enzymatic activity, providing a nitrogen source for UTP synthesis and thereby increasing UDP-GlcNAc generation." (PMID 40646162, 2025). "Moreover, together with the loss of growth arrest, the previous enhancement of maturation in the hepatoma line was significantly reduced as shown by decreased expression of maturation markers CYP3A4, ALB, AHR, GLUL, and PCK1." (PMID 38037844, 2024).
glioblastoma (16 papers, 2015 to 2026). The most malignant astrocytic tumor (WHO grade IV). "Among the genes studied, PER showed a transcriptional effect in glioblastoma cells by increasing the expression of BCAT1 and GLUL." (PMID 36831869, 2023). "This was in good accordance with the known high activity of glutamine synthase (GLUL) and the glutamate/cystine antiporter, competing for the intracellular glutamate in glioblastoma cells." (PMID 27027236, 2016). "To sum up, we identified seven genes (GRIA1, GRIA2, GRIK1, GRIK4, GRM3, GLUL, BCAT1) whose mRNA expression may serve as potential molecular biomarker candidates to distinguish glioblastoma and brain metastases tissue derived from surgical resections." (PMID 38835368, 2024). "Following 48 h of incubation with two different doses of anticonvulsants, significant effects could only be found in the expression of BCAT1, EAAT2 and GLUL in glioblastoma cells, whereas no changes in IDH1 and SLC7A11 expression were found." (PMID 30716120, 2019).
glioma (14 papers, 2016 to 2025). A benign or malignant brain and spinal cord tumor that arises from glial cells (astrocytes, oligodendrocytes, ependymal cells). "As a partner in crime, the glutamine synthetase (GS; encoded by GLUL) may be upregulated in high-grade glioma, whereas other malignancies presented mixed results." (PMID 38835368, 2024). "Previous studies have also confirmed that miR-140-5p and miR-29a-5p can bind to the 3′-UTR of GLUL, affecting the invasion and proliferation of glioma cells." (PMID 39519347, 2024). "While BCAT1 increases intracellular glutamate levels, promoting glioma proliferation, GLUL converts glutamate to glutamine, decreasing cytosolic glutamate levels." (PMID 36831869, 2023). "Additionally, CAF-specific GLUL knockdown attenuates tumor growth and extends median survival in a humanized orthotopic glioma model." (PMID 41355614, 2025). "Furthermore, GLUL-driven activation of PI3K/AKT signaling as the central regulator of CAF-mediated vascular niche formation is delineated in glioma progression." (PMID 41355614, 2025). "Additionally, miR-140-5p regulation of GLUL (glutamine synthetase) expression in glioma cells inhibits cancer cell proliferation, migration, and invasion." (PMID 39519347, 2024). "Human and mouse gliomas exhibit high rates of glucose catabolism, and use glucose to synthesize glutamine through glutamate-ammonia ligase (GLUL), which in turn promotes nucleotide biosynthesis via the pentose phosphate pathway independently of circulating glutamine." (PMID 30360490, 2018).
ovarian carcinoma (14 papers, 2018 to 2025). A malignant neoplasm originating from the surface ovarian epithelium. "By further evaluating the clinical significance of the ratio of GLN catabolism to anabolism, it was found that ovarian cancer patients with high GLS protein expression were associated with lower overall survival compared with patients having high GLUL protein expression." (PMID 36523985, 2022). "Indeed, co-inhibition of glutamine synthetase (GLUL) in CAFs and glutaminase (GLS) in ovarian cancer cells abrogated cancer cell growth better than each individual treatment." (PMID 33540679, 2021). "Surprisingly, GLUL levels, but not ASPA levels (Fig EV5A) in ascitic macrophages also correlated with the stage, indicating the GS represents a specific feature of protumoral macrophages in ovarian cancer." (PMID 34260142, 2021).
liver cancer (12 papers, 2011 to 2025). An epithelial or non-epithelial malignant neoplasm that arises from the liver. "We also demonstrated Fzd7 and GLUL are induced by p22 in vivo; this shows that genes associate with liver cancer (Fzd7) and β-catenin-mediated liver zonation and regeneration (GLUL,) are induced by p22 in normal hepatocytes." (PMID 32486480, 2020). "The study also demonstrated that Frizzled-7 (Fzd7) and Glutamate-Ammonia Ligase (GLUL), which have a known association with liver cancer and interact with TCF/β-catenin, are induced by p22 in vivo." (PMID 37112837, 2023). "Moreover, research has shown that YAP can reprogram glutamine metabolism to increase de novo nucleotide biosynthesis by inducing the transcription of glutamine synthetase (GLUL) in liver cancer." (PMID 40707702, 2025).
schizophrenia (12 papers, 2005 to 2025). A major psychotic disorder characterized by abnormalities in the perception or expression of reality. "The expression levels of two glutamate-related genes, Glutamate-ammonia ligase (GLUL) and glial high affinity glutamate transporter member 3 (SLC1A3) were decreased in suicide completers with schizophrenia." (PMID 17997842, 2007). "In the lactate shuttle, six (55%) of the significantly altered genes (n = 11) were upregulated: GLUL, LDHC, SLC16A3, SLC1A2, SLC1A3, and SLC2A1, which were collectively expressed in schizophrenia groups at a level of 1.5× higher than in control groups (LFC = 0.58)." (PMID 39125835, 2024).
pancreatic cancer (11 papers, 2017 to 2025). "A recent study showed that glutamate ammonia ligase (GLUL) expression is upregulated to promote PDAC cell growth upon Gln deficiency in samples from patients with pancreatic cancer and in mouse models." (PMID 39820281, 2025). "Supplementation with α-KG restored the growth and survival of glutamine-deficient pancreatic cancer cells with the help of glutamate-ammonia ligase (GLUL), which was elevated in the KRASG12D-induced mouse PDAC model." (PMID 37152291, 2023). "Enhanced expression of GLUL is also related to the malignant progression of pancreatic cancer, so targeting GLUL can effectively reduce the survival of pancreatic cancer cells." (PMID 36983244, 2023). "Pancreatic cancer cells with deletion of glutamate ammonia ligase (GLUL), a key enzyme of glutamine synthesis, show a significant reduction in the total level of O-GlcNAc as well as a reduction in tumor growth." (PMID 37838167, 2023). "On the other hand, pharmacological inhibition of OGT blocks the growth of pancreatic cancer cells with intact GLUL expression and function, suggesting a critical role of OGT and O-GlcNAc in the regulation of cancer cell growth by glutamine metabolism." (PMID 37838167, 2023). "Therefore, increased GLUL expression in pancreatic cancer patients and PDAC mouse models supplies glutamine to cancer cells to prevent glutamine deficiency." (PMID 39519347, 2024). "We used cell viability and colony formation assays to determine whether inhibiting GLUL activity affects pancreatic cancer cell growth and gemcitabine sensitivity." (PMID 39519347, 2024). "For example, pancreatic cancer cells rescue the glutamine deprivation crisis by de novo biosynthesis using α-ketoglutarate (α-KG) from the TCA cycle, which is mediated by glutamate-ammonia ligase (GLUL)." (PMID 36797531, 2023).